CD47 (CD47 molecule)
Diseases named in the same sentence as CD47 in open-access papers (continued):
Sharing a sentence is not in itself a finding about the gene and the disease.
tumor (continued). "The chemically modified exosomes were targeted to interfere with the CD47-SIRPα checkpoint on the surface of tumor cells, and their administration ameliorated engulfment of tumor cells by immune cells." (PMID 33537081, 2021). "RRX-001 is a nontoxic pleiotropic anticancer small molecule in phase 3 clinical trials (NCT03699956), including downregulating CD47 on tumor cells SIRP1α on TAMs." (PMID 33919979, 2021). "Many tumours have upregulated expression of CD47, a cell surface molecule that interferes with phagocytosis." (PMID 34452439, 2021). "In vivo studies of SL-172154 have demonstrated superior anti-tumor activity with the fusion protein over either CD47 antagonist, CD40 agonist antibody as monotherapy or the combination of the two, suggesting a synergistic role." (PMID 34944850, 2021). "Innate immune-checkpoint blockade with anti-CD47 antibodies have also shown activity in combination with rituximab by enhancing phagocytosis of malignant tumour cells in heavily pretreated DLBCL patients." (PMID 34572910, 2021). "The expression of CD47 on tumor cells inhibits myeloid cell-mediated elimination in a manner similar to that of PD-1/PD-L1 immune cell checkpoints that inhibit T-cell activity in tumors." (PMID 34943817, 2021). "Blocking this pathway with anti-CD47 antibody inhibited tumor growth in patient-derived xenografts of Gr.3-MB, ATRT, PNET, GBM and diffuse midline glioma (DMG)." (PMID 34830753, 2021). "CD47 blockade can therefore increase macrophage phagocytosis of FL tumor cells by rituximab and also induce a T-cell response by increasing tumor antigen presentation to cytotoxic T-cells." (PMID 33671658, 2021). "Blocking CD47 and SIRPα have since become promising avenues to induce killing of tumor cells, with several modalities now being trialed in patients." (PMID 34197341, 2021). "Microglia-derived TAMs are effector cells of tumor cell phagocytosis in response to anti-CD47 blockade." (PMID 33919979, 2021). "The combined use of the LSD1 inhibitor and anti-mouse CD47 mAb significantly enhanced the inhibition of tumor growth." (PMID 33731702, 2021). "NK cell-mediated lysis of luciferase-expressing tumor cells co-transfected with desired plasmid allowed investigation of the role of NK cells in CD47 blockade and opsonization via sCV1-hIgG1." (PMID 34729396, 2021). "A decrease of about one‐third in surface CD47 was previously reported to be effective in promoting tumor cell phagocytosis by macrophages." (PMID 33956406, 2021). "As a result of the promising preclinical data regarding the anti-tumor activity of CD47/SIPRα blockade obtained from in vivo and in vitro studies, several molecules have been developed and are undergoing clinical testing." (PMID 34944850, 2021). "Disruption of the CD47-SIRPα signaling axis results in the enhanced phagocytosis of both solid and hematopoietic tumor cells, leading to significant anti-tumor activity in vivo." (PMID 34885092, 2021). "It is well recognized that the innate immune regulator CD47 and the adaptive immune checkpoint PD-L1 regulate tumor immune responses through the SIRPα/CD47 and PD-1/PD-L1 pathways, respectively." (PMID 33731702, 2021). "The prevailing model proposes that high CD47 expression on tumor cells engages the inhibitory counter-receptor SIRPα on phagocytes to prevent tumor cell killing." (PMID 33925464, 2021). "Disrupting the CD47-SIRPα ligand promotes the phagocytosis of tumor cells and immunity-mediated antitumor effects." (PMID 34452008, 2021). "The latest tumor research uses CD47 to modify nanoparticles, which reduces the clearance rate of nanoparticles by macrophages." (PMID 34239692, 2021). "SIRPα inhibits the phagocytic activity of macrophages when interacting with its ligand CD47 which can be expressed on tumor cells." (PMID 34440251, 2021). "Binding of CD47 to its receptor signal regulatory protein a (SIRPa) on macrophages inhibits phagocytosis activation and can contribute to tumor formation." (PMID 33805268, 2021).
tumor (continued). "It is recently discovered that the tumor conveys the "don't eat me" signal of innate immune surveillance through CD47‐SIRPα5 and CD24‐Siglec‐106 action." (PMID 34363319, 2021). "Given the wide therapeutic potential of anti-CD47 monoclonal antibody, one that effectively block the CD47 on tumor cells while sparing erythrocytes would be desirable." (PMID 33790906, 2021). "Although CD47 has some impact on the proliferation and migration of tumor cells, it functions in cancer cells as a cell surface ligand." (PMID 33629544, 2021). "In this study, we demonstrate that the engagement on the surface of tumor cells of the CXCR4 receptor induces the depletion of surface CD47, the molecule that physiologically prevents phagocytosis by macrophages." (PMID 33956406, 2021). "In vivo data indicated that the fusion protein was able to block CD47 and impair the tumour growth in several haematological xenograft models, including AML, BL and DLBCL." (PMID 33430146, 2021). "CD47 is expressed on tumor cells and presents a ‘don’t eat me’ signal to the macrophages, hence enabling the tumor cells to escape phagocytosis." (PMID 33708214, 2021). "After exposure to NTP, the CD47 expression on the surface of cancer cells was immediately reduced in 3D in vitro tumor models." (PMID 33540720, 2021). "Beyond the activation of macrophage-mediated tumor killing, CD47-SIRPα interruption exerts other multidimensional positive effects on the immune response against cancer cells." (PMID 34944850, 2021). "Meanwhile, tumor cells highly express CD47, which is the ligand of signaling regulatory protein α (SIRPα), an immune checkpoint found on macrophages." (PMID 34062992, 2021). "The CD47‐SIRPα signaling pathway is an important mechanism of immune escape for high CD47‐expressing tumor cells." (PMID 33629544, 2021). "For example, the pH-responsive exosome nano-bioconjugates composed of M1 macrophages-derived exosomes with antibodies of anti-CD47 and anti-SIRPα through acid-cleavable benzoic-imine bonds has been developed to target the tumor cells." (PMID 34852849, 2021). "Once tumor cells that express the CD47 antigen on their surface encounter macrophages, CD47 binds to SIRPα which leads to the transmission of the “do not eat me” signal and consequent abrogation of phagocytosis by macrophages." (PMID 33869011, 2021). "The binding of the bispecific anti-PD-L1-SIRPα fusion protein to both of PD-L1 and CD47 on cancer cells significantly enhances antitumor activity in MC-38 colon cell xenograft tumor model." (PMID 34512146, 2021). "Quorum-sensing bacteria that delivers single chain antibody fragments targeting CD47 has also been tested with increased anti-tumor immunity and reduced progression." (PMID 34944850, 2021). "By engaging SIRPα, CD47 limits the ability of DCs and macrophages to engulf tumor cells, which acts as a major phagocytic barrier." (PMID 34078376, 2021). "Signal regulatory protein α (SIRPα) on macrophages serves as a receptor of CD47 to transduce CD47/SIRPα axis mediated inhibitory function of macrophage phagocytosis of tumor cells." (PMID 33763066, 2021). "The survival of CCR2RFP/RFPCX3CR1GFP/wt mice was significantly prolonged after treatment with anti-CD47 antibody, suggesting that tumor phagocytosis by microglia contributes to recovery from brain tumors." (PMID 34685535, 2021). "When CD47 binds to signal regulatory protein α on phagocytes, it can inhibit the phagocytosis of tumor cells by macrophages to promote tumor proliferation." (PMID 33796465, 2021). "In a mouse model of lymphoma, the bispecific anti-CD47/SIRPα antibody inhibited tumor growth and spread by targeting the multiple myeloid cell types in the tumor." (PMID 34683963, 2021). "Anti-CD47 antibodies can induce the phagocytosis of tumor cells by the blockade of CD47 and its ligand, SIRPα." (PMID 34830980, 2021).
tumor (continued). "Since antibodies targeting CD47 are an emerging field of immune-oncology through the promotion of tumour phagocytosis, it will be of interest to determine the extent to which macrophages are involved in tumour clearance following PIT." (PMID 33836238, 2021). "CD47-SIRPα myeloid checkpoint blockade has been shown to effectively enhance tumor phagocytosis and reduce tumor burden." (PMID 34625564, 2021). "In principle, a syngeneic tumor model would also be applicable, as we also demonstrated sCV1-hIgG1 binding to murine CD47 on CT26 cells." (PMID 34729396, 2021). "In patient-derived xenograft models, CD47 blockade as monotherapy has proven unsuccessful in regard to tumor volume control and durability." (PMID 33748077, 2021). "Our finding that CD47 blockade failed to recapitulate the phenomenon of tumor eradication by RT-activated Sirpα−/− macrophages, however, strongly argue that SIRPα controls tumor responses to RT via a CD47-independent pathway." (PMID 34050181, 2021). "A growing number of studies have demonstrated that inhibiting the CD47-SIRPα signaling pathway promotes the adaptive immune response and enhances the phagocytosis of tumor cells by macrophages." (PMID 33562694, 2021). "In the meantime, CD47, as a “don’t eat me” signal, protects tumor cells from phagocytosis by macrophages, which has become a new mechanism of tumor development and development, and has also explored a new effective way for tumor immunotherapy." (PMID 34194437, 2021). "Recent studies have emphasized the role of the inhibitory receptor SIRPα in regulating macrophage phagocytosis of tumor cells that highly express CD47." (PMID 33925464, 2021). "CD47 is often overexpressed on tumor cells and interacts with SIRPα on myeloid cells to trigger a ‘don’t eat me’ signal." (PMID 33936033, 2021). "CD47 is often expressed on the surface of tumor cells; CD47-SIRPα releases a “don’t eat me” signal to DC cells, thus evading recognition by DC cells." (PMID 34025638, 2021). "To the best of our knowledge, this study is the first one of its kind in that we have specifically investigated the role of the CD47/SIRPα axis in the VES-induced anti-tumour effect." (PMID 34093795, 2021). "DSP107 binds to CD47 with subsequent removal of the inhibitory signal delivered to phagocytes on tumor cells." (PMID 34207500, 2021). "The highly expressed CD47 on the surface enables tumor cells to evade from immune surveillance of macrophages." (PMID 34776955, 2021). "CD47 on the tumor cell surface binds to SIRPα on the surface of macrophages, which activates the Src homology region 2 (SH2) domain phosphatases SHP1 and SHP2 and thereby transmits a “don’t eat me” signal to macrophages." (PMID 35070992, 2021). "Anti-CD47 antibodies have been developed to shift macrophages to an immunostimulatory phenotype, promoting an anti-tumor response and effectively reducing growth of several tumors." (PMID 34298615, 2021). "One strategy to overcome this hurdle is the simultaneous targeting of another tumor antigen, which increases the specificity of treatment to tumor cells and limit interaction with other CD47 expressing normal cells." (PMID 34584838, 2021). "Nonetheless, clinical trials that are currently being explored with antibodies targeting the CD47-SIRPα axis from the CD47 side in combination with tumor-specific monoclonal antibody therapy have shown minimal to moderate toxicity effects." (PMID 34503071, 2021). "Dependent on activation FcγR, the binding of SRF231 to CD32a on macrophage has a dual role: inducing FcγR-mediated phagocytosis of cancer cells and used as a scaffold to drive CD47-mediated death signals into tumor cells." (PMID 34717705, 2021). "PLTs are disc-shaped and changeable, with a diameter of approximately 1-4 μm, and express membrane proteins such as p-selectin and CD47, which identify injured blood vessels and circulating tumor cells (CTCs)." (PMID 34142930, 2021).
tumor (continued). "A CD47/SIRPα blockade provokes antitumor activity by inducing tumor cell phagocytosis by macrophages and activating the cross-presentation of tumor antigens to CD8+ T cells by DCs." (PMID 35008305, 2021). "Amplified MYC was recently shown across several tumor models to directly upregulate CD47 and PD-L1 in cancer cells, which served to suppress recruitment and promote exhaustion of T cells." (PMID 34299381, 2021). "By this means, TAMs at the tumor resection sites can be reeducated by sorafenib first, followed by overcoming tumor immune escape via CD47 blockade, thereby establishing an overall immune-favorable microenvironment for enhanced therapeutic outcomes." (PMID 34138357, 2021). "Results showed that VES reduced tumour growth, increased overall survival and inhibited CD47 in the tumour transcriptionally and translationally." (PMID 34093795, 2021). "The receiver operating characteristic region under the curve (ROC AUC), for multiplexed molecular imaging of CD47 and Carbonic Anhydrase 9 tumor proteins was 0.93." (PMID 34063088, 2021). "Peptide mimetics of TSP1 and CD47 antibodies that directly induce tumor cell death are being explored as potential cancer therapeutics." (PMID 33925464, 2021). "Currently, antibodies that antagonize the CD47-SIRPα interaction were found to induce the antibody-dependent cellular phagocytosis (ADCP) of tumor cells, and the priming of tumor-specific T-cell responses." (PMID 34248142, 2021). "A high affinity to PD-L1 and lower affinity to CD47 allowed IBI322 to selectively bind CD47 + PD-L1 + double positive tumor cells, even in the presence of CD47 + RBCs." (PMID 34584838, 2021). "A recent study defined a novel mechanism of high-dose cyclophosphamide promoting macrophage phagocytosis-dependent lymphoma clearance by shifting the balance of pro- and antiphagocytic factors, which includes downregulation of CD47 on tumor cells." (PMID 33919979, 2021). "This enhanced phagocytosis also leads to increased antigen cross-presentation and T cell priming, and anti-CD47 therapies have shown synergy with autophagy inhibition, as well as other ICIs and tumor-specific antibodies." (PMID 34298615, 2021). "IBI322, an anti-CD47/PD-L1 bispecific monoclonal antibody, was designed with a monovalent CD47-binding domain and bivalent PD-L1-binding domain, to enable selective tumor targeting and spare red blood cells." (PMID 34944850, 2021). "Subsequently, expression of CD47 allows tumor cells to increase their stemness and escape phagocytosis." (PMID 34595122, 2021). "CD47-SIRPα blockade using CD47 antibodies was shown to restore phagocytosis of tumor cells by TAMs in vitro, stimulate antigen-specific T cells and limit tumor growth in murine models." (PMID 33572196, 2021). "In one report, using engraft animal models established via injecting the selected CD90high PanNET cell (cancer stem cell) with higher expression of CD47, anti-CD47 antibody inhibited PanNET tumor growth in animal model." (PMID 33765961, 2021). "We found CD47-SIRPα interactions between neutrophil and tumor cells to limit the neutrophil’s capability of inducing antibody-mediated cytotoxicity in vitro." (PMID 34503071, 2021). "The use of anti-CD47 mAb to control the growth of human tumor xenografts in NOD SCID gammaTM mice was therapeutically efficacious for medulloblastoma, glioblastoma, ovarian, bladder, colorectal and breast tumors." (PMID 34638388, 2021). "Owing to potent nanobody‐mediated blockade of CD47, authors observed increased activation of tumor‐infiltrating T cells, durable and systemic anti‐tumor immunity, and rapid tumor regression." (PMID 33854892, 2021). "Next, they enhanced tumor phagocytosis by TAMs by treatment with anti-CD47 antibodies, which increased the percentage of microglia and macrophages that infiltrated and phagocytosed tumors." (PMID 34685535, 2021).
tumor (continued). "Blockade of CD47 has been shown to restore phagocytosis and the clearance of tumor cells, and to induce tumor regression in several preclinical cancer models." (PMID 34638388, 2021). "The velcro-CD47 demonstrated anti-tumor activity and synergy with tumor-specific monoclonal antibodies (trastuzumab or cetuximab) in tumor cell lines." (PMID 34944850, 2021). "Meanwhile, CD47-blockade has only exhibited modest anti-tumor activity, as a monotherapy, since the effect of CD47-blockade is limited." (PMID 34349643, 2021). "The macrophage immune checkpoint inhibitor, magrolimab, is a humanized monoclonal antibody against CD47, a cell surface receptor involved in inhibiting tumor-cell phagocytosis by macrophages and dendritic cells." (PMID 34945817, 2021). "Nano engineering technology combined with exosomes for drug delivery, targeting tumor stem cells. aCD47 and CD47 on the surface of tumor cells are specifically recognized, and nano-bio-conjugate can actively target tumor cells." (PMID 33828985, 2021). "Effects of TSP1 on cell metabolism in the tumor microenvironment can be extrapolated from studies examining the role of CD47 on cellular bioenergetics." (PMID 33925464, 2021). "In this line, it has been reported that CD40 agonist antibodies activate antitumor macrophages and other antibodies inhibit the CD47 surface molecule in tumor cells, leading to macrophage-mediated tumor cell phagocytosis." (PMID 34677429, 2021). "Anti-CD47 antibodies induce an antitumor T cell response by the cross-presentation of tumor antigens by phagocytes to T cells." (PMID 33562694, 2021). "CD47 expressed on the tumor cells serves as a ligand for the SIRPα immune inhibitory receptor, which is expressed on macrophages." (PMID 33629544, 2021). "One such approach involves blocking the binding between CD47 and signal regulatory protein alpha (SIRPα), increasing tumor cell phagocytosis by macrophages." (PMID 33801234, 2021). "Recently, Hu5F9-G4, a humanized IgG4 monoclonal antibody against human CD47, was examined in phase I studies, and it displayed anti-tumor effects against both hematological and solid malignancies." (PMID 33799989, 2021). "Recent studies have focused on overexpressed CD47, which plays a key role in immune response in tumor cells." (PMID 33936211, 2021). "CD47 is a transmembrane protein found ubiquitously expressed on normal cells as a “self” marker, but it is also overexpressed by tumor cells." (PMID 34572939, 2021). "Among many interactions, besides those of the integrins and signal regulatory protein α (SIRPα), CD47 binds thrombospondin-1, a potent gatekeeper of tumor progression." (PMID 34885092, 2021). "Many inhibitors have been developed to block the CD47‐SIRPα pathway and enhance tumor immunotherapy, including anti‐CD47 therapy and anti‐SIRPα therapy." (PMID 34579759, 2021). "Currently, disrupting the CD47/SIRPα interaction has become a new antitumor immunotherapy strategy that induces the phagocytosis and elimination of tumor cells." (PMID 34943817, 2021). "Further, the results showed that an LSD1 inhibitor (ORY-1001) combined with anti-CD47/PD-L1 monoclonal antibodies inhibited tumor growth in an established subcutaneous xenograft model more effectively than a single blockade strategy." (PMID 33731702, 2021). "In contrast, cancer cell–expressed miR-128 inhibits metastatic program by directly targeting ZEB1, a positive regulator of EMT and CD47-mediated tumor immune evasion." (PMID 34591242, 2021). "SIRPα expression was limited to tumor oligodendrocytes and myeloid cells, while its ligand, CD47, was ubiquitously expressed within the tumor microenvironment." (PMID 34917090, 2021). "SIRPA’s phosphorylation status is relatively low in resting phagocytes but is greatly enhanced by binding to the membrane protein CD47 on targets such as tumor cells." (PMID 34097709, 2021). "Necrosis was observed in the center of the only tumor in the SNALPssiCD47-Dox group and low CD47 expression was detected." (PMID 34522209, 2021).